ENSG00000277188
Gene: Miscellaneous RNA gene on chromosome 5 (76,712,195 to 76,712,327, forward strand). Ensembl gene ENSG00000277188.
Gene Ontology:
Biological process: positive regulation of gene expression